CD4 (CD4 molecule)
Diseases named in the same sentence as CD4 in open-access papers (continued):
Sharing a sentence is not in itself a finding about the gene and the disease.
tumor (continued). "Tregs inhibit the activation and differentiation of CD4+ helper T and CD8+ cytotoxic T cells, thereby inducing responses to autologous and tumor-expressed antigens." (PMID 37671150, 2023). "The infiltration of CD4+ and CD8+T cells is a crucial part of the anti-tumor immune response that induces tumor cell apoptosis." (PMID 37719125, 2023). "CD27 is not only constitutively expressed on the majority of both CD4+ and CD8+ T cells, but is also highly expressed on the majority of tumor infiltrating lymphocytes (TILs)." (PMID 37545491, 2023). "Correlations were observed between FDX1 expression and B cell, CD4+T cell, CD8+T cell, neutrophil, macrophage, and dendritic cell (DC) infiltration in multiple cancers, suggesting a potential role in the tumor immune microenvironment." (PMID 36825202, 2023). "Knockdown of PAK1 increases intratumor CD4+ and CD8+ TILs and eliminates the protective effect of pancreatic stellate cells (PSCs) on tumor cells, allowing them to be killed by the immune system." (PMID 37529035, 2023). "Upon subcutaneous injection of a syngeneic B16- ovalbumin melanoma tumor, inulin uptake promoted infiltration of CD4+ and CD8+ T cells and increased IFN-γ production, thereby triggering an effective Th1 anti-tumor response and inhibiting tumor growth." (PMID 37638034, 2023). "In our study cohort, we observed significantly lower levels of CD4+ and CD8+ cells in the tumor center compared to the invasion front." (PMID 36836239, 2023). "Our study also demonstrated a potential relationship between P4HA2 expression and tumor immune cell infiltration since P4HA2 expression showed a positive correlation with the levels of macrophages, neutrophils, B, CD4+, and dendritic cells in the HCC tissues." (PMID 37248456, 2023). "Although the absolute cell counts of CD4+ and CD8+ T cells were approximative in tumor thrombus and primary tumor, the primary tumor had relatively higher proportions of CD4+ and CD8+ T cells." (PMID 37244923, 2023). "More specifically, pGSN within the tumour downregulates the anti-tumour functions of immune cells in the tumor microenvironment (CD8 + T cells, CD4 + T cells, dendritic cells and M1 macrophages)." (PMID 36642715, 2023). "LAG-3 is a type I transmembrane protein with four Ig-like domains expressed on exhausted CD4 and CD8 tumor-infiltrating T-cells and T-regs in peripheral blood and tissue, contributing to immunoescape mechanisms." (PMID 38067208, 2023). "Previous studies showed that activated CD4+ T cells from HCC interact with macrophages in laboratory mice, leading to cytokines produced by macrophages that reduce the anti-tumor immune response." (PMID 37406019, 2023). "As most tumor cells lack expression of MHC class II, in most cases, the effect of CD4+ T cells is limited to their release of cytokines." (PMID 37727790, 2023). "Meanwhile, the RBC‐Nanovaccines plus anti‐PD‐1 remarkably enhance the repertoires of IFN‐γ+CD4+ T cells and IFN‐γ+CD8+ T cells, thus potentiating the adaptive immune response for tumor control." (PMID 37552209, 2023). "NIR-PIT using an antibody–photoabsorber conjugate that targets CD25 selectively depletes the CD4+CD25+Foxp3+ Tregs infiltrating the tumor microenvironment and activates CD8+ T cells and natural killer (NK) cells, resulting in local anti-tumor immunity." (PMID 36839882, 2023). "This analysis revealed an increased infiltration of CD45+ T cells, CD4 + T cells and CD8 + T cells were observed in the tumours of mice treated with LCAR-M23 CAR T cells, compared to those of mice treated with F3M CAR T cells or UnT cells." (PMID 36166071, 2023). "As expected, tumoral ATXN3 deletion resulted in a significant increase in CD4+ and CD8+ T cell tumor infiltration." (PMID 38038129, 2023). "This cellular subpopulation was not detectable in T cells from ascitic fluid nor in peripheral blood of the same patients (CD8+: p<0.001 for tumor vs both PBMC and ascites, CD4+: p=0.02 for tumor vs ascites and p=0.01 for tumor vs PBMC)." (PMID 37868997, 2023).
tumor (continued). "Using intravital microscopy, we found that CD4+ and CD8+ effector T cells differ fundamentally in their mode and their site of action in tumour tissues." (PMID 37316667, 2023). "The two SwR-CAR constructs (JK59 and JK69) were expressed at similar levels and conferred both CD4+ and CD8+ T cells with STEAP1-specific anti-tumor activity." (PMID 36830995, 2023). "In contrast, the CD4+ and CD8+ T cells in tumor dLN remained poorly activated, and their numbers were comparable between WT and Zeb1-dcKO tumor-bearing mice." (PMID 37863917, 2023). "Another interesting result is that MyxV_CD47, contrary to our expectations, evoked more CD4+ T-cells than MyxV_IFN-γ, and even increased the IFN-γ+ CD4+T-cell population in the tumor." (PMID 37835397, 2023). "Pharmacological inhibition and knockout of DDR1 increased the tumor burden, with DDR1 knockout tumors showing a decrease in CD8+ cytotoxic T cells and an increase in CD4+ helper T cells and regulatory T cells." (PMID 38136314, 2023). "Compared with PAMcluster-B and PAMcluster-C, PAMcluster-A had higher levels of CD4 + T cells and CD8 + Tcells, indicating stronger tumor immune function." (PMID 37202800, 2023). "Within the tumor microenvironment, TGF selectively attracts Treg cells and promote an in-situ transformation of CD4+ T cells into suppressive T cells (Treg)." (PMID 37029378, 2023). "In high MYO5A expression HNSC, there was a low count of tumor infiltrating lymphocytes (TIL), including activated CD4+ T cells, CD8+ T cells, and B cells." (PMID 38129784, 2023). "Cisplatin induces an increase in CCL20 and IL-1β in tumor cells within a cold tumor model, both of which activate ILC3s to release the chemokine CXCL10, attracting CD4 T and CD8 T lymphocytes to infiltrate tumor tissue and then exert anti-tumor effects." (PMID 37122757, 2023). "The frequencies of memory T cell subsets and that of PD-1H+ cells in the total CD4+ and CD8+ T cell pools isolated from tumor-draining lymph nodes (dLNs) were analyzed by flow cytometry." (PMID 37046033, 2023). "The immune-inflamed phenotype is characterised by a TME where immune cells (especially CD4+ and CD8+ T cells) and cancer cells are in close proximity within the tumour parenchyma." (PMID 37143952, 2023). "In conclusion, we found that propolis, a natural supplement, potentially prevented CRC progression by increasing CD3+ and CD4+ TILs and reducing FOXP3 lymphocytes in the tumor microenvironment of early stage CRC." (PMID 37960147, 2023). "Th1-polarized CD4+ cells, on the other hand, promote macrophage cytotoxicity by secreting cytokines such as TNF, which binds cytotoxic CD8+ T cells that have anti-tumor effects in vivo." (PMID 37225919, 2023). "Compared to PBMCs, the ratio of exhausted CD4+ and CD8+ T cells are significantly higher in tumor regions." (PMID 38188300, 2023). "The expansion of malignant CD4 T cells results in increased CD4:CD8 T cell ratios and the presence of atypical tumor cells in the blood." (PMID 37654486, 2023). "Though AB680@EMVs-aPD-L1 didn’t show a significantly better tumor inhibition effect than free AB680 + aPD-L1, it had a longer median survival and CD8+/CD4+ ratio in tumor tissues." (PMID 37106400, 2023). "Staining of LLC tumor sections showed that TPP‐LND@Lip significantly enhanced the infiltration and activation of CD3+, CD4+, and CD8+ T cells in the tumor microenvironment after radiotherapy." (PMID 37092578, 2023). "The aggregation of CD4 + T cells and CD8 + T cells enhanced immune capacity and anti-tumor activity in NB." (PMID 37990103, 2023). "Many prior studies have reported that CD4+ T cells inhibit HCC initiation and restrain tumor progression." (PMID 37266440, 2023). "NE(PD1nb) activate dendritic cells (DCs) differentiation and stimulate the M1‐like differentiation of macrophages, and induce CD4+ T‐cells maturity and cytotoxic CD8+ T‐cells activation through DCs tumor antigen presentation." (PMID 37565362, 2023).
tumor (continued). "The anti-GITR antibody in tumor-bearing mice can break immunological self-tolerance and evoke a potent anti-tumor immune response with an increase in IFN-γ-producing CD8+ and CD4+ T cells." (PMID 36839882, 2023). "It has been clearly demonstrated that the degree of tumour hypoxia correlates with immunosuppressive M2 macrophage infiltration, while it is inversely proportional with intratumoral CD4+ and CD8+ T cells, the main mediators of anti-tumour immunity." (PMID 36817445, 2023). "Treatment of a syngeneic GB mouse model (CT-2A) with ITI-1001 resulted in increased antigen presentation, multi-antigen-specific CD4 and CD8 T cell responses, and around 56% long-term survival in tumor-bearing mice." (PMID 38074665, 2023). "Mechanistically, ICT works by enhancing the anti-tumour effector functions of CD4+ and CD8 + T cells, initially formed during their first contact (priming) with tumour peptides complexed with major histocompatibility complex (MHC) molecules." (PMID 37454231, 2023). "A previously published report demonstrated that a functional immune crosstalk between CD4+ and CD8+ T cells is crucial in mediating the anti-tumor responses by MIP." (PMID 37122749, 2023). "Our results show that CD45+, CD4+, and CD8+ T cells were increased in tumor tissues after cisplatin treatment, and the proportions of CD45+ and CD8+ T cells were significantly increased in the shIDH3α+CDDP group." (PMID 36980689, 2023). "Among the 26 patients, 21(80.8%) had evaluable tumor biological samples to analyze the expression of PD-L1, VEGFR-2, CD4 and CD8 expression." (PMID 38239359, 2023). "Accordingly, Cluster 2 (immune suppressed) and Cluster 4 (immune cold) showed a higher ratio of neutrophils/T-cells (CD4+ and CD8+) compared with Cluster 1 (immune hot) and Cluster 3 (immune moderate) tumours (Kruskal–Wallis, p = 0.00013)." (PMID 37258531, 2023). "Characterized by the co-expression of surface markers CD4, CD25, and FOXP3, Treg was revealed to be correlated with the poor prognosis of RCC probably through assisting the immune escape of tumor cells." (PMID 37305457, 2023). "CD4+ T cell frequency and the CD4+ to CD8+ T cell ratio at the tumor boundary served as a prognostic indicator and suggested T cell activity at the tumor boundary is critical to a productive immune response." (PMID 36414691, 2023). "The second and third marked distinction between current analysis and the result with sole OVT are related to the parameters δc, the tumor killing rate by cytokines, and αy, the IFN-γ proliferation rate by CD4+ T cells, respectively." (PMID 36766849, 2023). "In Nrf2- activating MU group, there were fewer immune cells with dominant anti-tumor activity, such as Tregs, Th2 cells, Th1 cells, NK cells, Monocytes, T cells, CD8 + T cells, CD4 + T cells, and B cells (all p < 0.05)." (PMID 37794491, 2023). "Activated memory CD4+ T cells can boost cognate memory CD8+ T cell expansion and improve tumor control." (PMID 35635121, 2023). "Reports show that tumor cells and virus-infected cells can express MHC II and become targets for CD4+ CTL killing." (PMID 37965314, 2023). "Furthermore, coexpansion of Tregs and cDC2‐like mregDCs results in tumour immune tolerance, while therapeutic depletion of Tregs effectively augments cDC2 maturation and reverses the phenotypic dysfunction, thereby facilitating the production of antitumour CD4+ T cells." (PMID 36808888, 2023). "This superior protection was attributed to the induction of prominent tumor-reactive CD8+, and CD4+ T-cell responses as detected in BALF and the lung parenchyma of CpG-NP-Tag-immunized mice." (PMID 36839766, 2023). "On day 18 post MC-38 tumor challenge, the percentage of CD8+ and CD4+ T cells within the circulating leukocytes in blood and spleen increased after PDOX treatment compared with no treatment and anti-PD-L1 treatment." (PMID 36796366, 2023). "Next, we analyzed the effect on tumor-infiltrating T cells (CD8 and CD4 TILs) by immunofluorescence microscopy." (PMID 36305874, 2023).
tumor (continued). "The data provided evidence that an agonistic humanized anti-OX40 mAb used prior to surgery was therapeutically safe and increased activation and proliferation of CD4+ and CD8+ T cells in the blood and tumour milieu." (PMID 36980527, 2023). "Similar observation in CD8+ T cell response to ICB, CD4+ T cells have also been reported to be required for ICB, especially CTLA‐4 blockade in tumor patients." (PMID 37829505, 2023). "4T1 tumor-bearing mice were treated with a-TEA-Lys in the presence or absence of aPD-1 and then 7 days post-treatment, tumors were harvested and CD4+ and CD8+ T cell responses were evaluated by flow cytometry." (PMID 36911733, 2023). "ICIs inhibit T effector cell replacement by T regulatory cells, activate dendritic cells, and activate tumor-infiltrating cytotoxic CD8+ and CD4+ T cells." (PMID 37760424, 2023). "Tumor-mediated immunosuppression could be caused by the release of immunosuppressive cytokines, such as TGF-β and IL-10; the expression of immune checkpoint inhibitors, such as programmed cell death protein 1 (PD-1); or by the presence of immunosuppressive cells, such as CD4+ Treg cells." (PMID 37238744, 2023). "In particular, patients in the low-CAFRS group had a higher abundance of tumor-infiltrating CD8+ T cells and CD4+ T cells and a lower abundance of macrophages, especially M2 macrophages." (PMID 38235137, 2023). "The aggregation of CD4 + T cells and CD8 + T cells enhanced immune capacity and anti-tumor activity in CM." (PMID 36717900, 2023). "CD4+ T cells are crucial to immune memory and CD8+ T cells are essential for protection against viruses, intracellular bacterial infection, and tumor cells." (PMID 36726304, 2023). "This approach effectively controls EBV-related tumors, targets and efficiently eliminates EBV-related tumor cells through the FasL and TRAIL pathways and promotes the expansion of EBV antigen-specific CD4 and CD8 T cells." (PMID 38087360, 2023). "The survival module was used to look at the clinical significance of tumor immune subsets (CD8+ T cell, CD4+ T cell, macrophage, B cell, neutrophil, and dendritic cell) in BRCA-Her2, KIRC, KIRP, LUAD, THCA, and THYM." (PMID 37624423, 2023). "Tumor infiltration levels differed with different CNV of COL10A1, infiltration levels of CD4+ T cell (P<0.01) were lower with chromosome arm-level deletion and gain of COL10A1." (PMID 37006317, 2023). "Furthermore, detailed knowledge of natural HLA class II antigen presentation patterns will allow for tailoring multi-epitope peptide vaccines containing both HLA class I- and HLA class II-restricted targets, which may induce and boost synergistic CD8+ and CD4+ anti-tumor responses." (PMID 37368072, 2023). "Anti-tumor cells are effector T-cells, including cytotoxic CD8+ T-cells and effector CD4+ T-cells, natural killer cells (NK), dendritic cells (DCs), and macrophages." (PMID 37958406, 2023). "As CD4+ Th1 cells also express the chemokine receptor CXCR3, Th1 cells enter the tumor and become activated." (PMID 37511431, 2023). "Through appropriate intervention epigenetic modification, these drugs can regulate the activity of CD4+ and CD8+ T lymphocytes and NK cells to exert anti-tumor effects." (PMID 37131252, 2023). "The increase of CD4+ and CD8+ T cells and the decrease of Treg cells after cryoablation are important for tumor control and patient survival." (PMID 36761748, 2023). "CD103, a marker for TRM cells with increased tumor antigen sensitivity and improved response to immunotherapy, was more prevalent in CD8+ than CD4+ cells in overall HPB patients." (PMID 36798126, 2023). "We first evaluated infiltration of host CD45.2+ CD4+ and CD8+ T cells into CT-2A tumours treated with i.t. amph-FITC and CD45.1+ CAR T cells." (PMID 37291434, 2023). "The abundance of several anti-tumor immune effectors, including CD8/CD4 T-cells, activated NK-cells, and M1 macrophages were significantly higher in C1, compared to C2." (PMID 37903125, 2023).
tumor (continued). "The result demonstrated the inhibitory effect of HERC2 on anti-tumor immunity, as indicated by impaired activation of CD8+ T cells, CD4+ T cells, and NK cells in the coculture system of PBMCs with HERC2-overexpressed HCC cells." (PMID 36721234, 2023). "We found that knockdown of Caprin-1 slightly inhibited tumor growth, while the expression of LC3, as well as infiltrated numbers of CD4 and F4/80 positive cells were dramatically reduced." (PMID 38082307, 2023). "As the equilibrium between different T cell subsets is involved in the final outcome of the tumor immune response, CD8+/CD4+, CD8+/Foxp3+, and Foxp3+/CD4+ ratios were calculated." (PMID 36508123, 2023). "In the same context, the infiltration of T-cell subpopulation in tumor tissue showed a significant decrease in tissue CD3+, CD4+, and CD8+ cells." (PMID 37068081, 2023). "The proportion of CD4+ T cells displayed an increasing trend, while the proportion of CD8+ T cells showed a decreasing trend in tumor samples." (PMID 37533434, 2023). "Anti-GDF-15 treatment indeed enhanced the trafficking of CD4+ and CD8+ T cells to tumor-draining lymph nodes." (PMID 37474523, 2023). "Obviously, sgCas9‐AdV/Gel injection elevated the levels of CD3+CD4+ (helper) and CD3+CD8+ (cytotoxic) T cells in tumor tissues, while reducing the infiltration of Tregs." (PMID 36840638, 2023). "The other two articles evaluated CD4+ and CD8+ T cell populations in both stroma and tumor tissue and reported a significant increase after the first cycle of NAC in both populations." (PMID 37104271, 2023). "CD4+ CAR-T cells outperformed CD8+ CAR-T cells, especially regarding long-term tumor eradication and survival of treated mice." (PMID 37443804, 2023). "Overall, the abundances of CD8 T cells, resting memory CD4 T cells, activated NK cells, M1 macrophages, and eosinophils were significantly reduced in PTC tumor tissues compared with adjacent normal tissues." (PMID 36975413, 2023). "The immunohistochemical expression of CD8, CD4 and FOXP3 positive cells was evaluated in tumor tissue samples in relation to radiological treatment." (PMID 36717781, 2023). "Ectopic ACTH expression and infiltration of CD3+, CD4+, CD8+, and CD20+ lymphocytes were observed in the tumor tissues and circulating anti-POMC antibodies were detected specifically in the patient’s serum." (PMID 38035072, 2023). "Although various pre-clinical and clinical studies have shown an increased number of HPV-specific CD4+ and CD8+ T cells after immunization, with proportional cytokine secretion, the activity of tumor-therapeutic vaccines against established tumors is limited." (PMID 37513985, 2023). "Tumor-infiltrating immune cells, such as CD8+ T cells, CD4+ T cells, and macrophages, are important components of the tumor microenvironment and can affect tumor progression and patient prognosis." (PMID 38188686, 2023). "Propolis potentially prevented CRC progression by increasing the levels of CD3+ and CD4+ TILs and reducing the levels of FOXP3 lymphocytes in the tumor microenvironment in early stage CRC." (PMID 37960147, 2023). "Increasing evidences demonstrate that pyroptosis plays an essential role in anti-tumor immunity, and pyroptosis-induced tumor regression requires CD8+ T cytotoxic cells, CD4+ T helper cells and also Asialo-GM1+ nature killer cells." (PMID 37495617, 2023). "Consistent with the tumor growth inhibition, anti-PD-L1 therapy promoted the tumor accumulation of CD8+ T cells and the combination of PD-L1 blockade and CD4+ T cell depletion further increased the proportion of intratumoral CD8+ T cells." (PMID 36969495, 2023). "Compared with unmodified exosomes, CIITA-exosomes increased IFN-γ-producing CD4 + T cell and tumour antigen (TYRP2)-specific CD8 + T cell populations, and prolonged survival rate of the tumour-bearing mice." (PMID 37022605, 2023).